CD33 (CD33 molecule)
Diseases named in the same sentence as CD33 in open-access papers (continued):
Sharing a sentence is not in itself a finding about the gene and the disease.
acute myeloid leukemia (continued). "Associated to the humanized mAb lintuzumab, the corresponding targeted 227Th conjugate (227Th-lintuzumab or CD33-TTC) was studied for the targeting of CD33, a sialic acid transmembrane receptor expressed in blood cancers and especially acute myeloid leukemia." (PMID 34207408, 2021). "Sun and colleagues conjugated liposomal daunorubicin with CD123/CD33 antibody by thiolation, and attained 1.8-fold higher cellular uptake and 1.53-fold (P < 0.001) greater cytotoxicity against acute myeloid leukemia (AML) cells." (PMID 33422061, 2021). "The first ADC Gemtuzumab ozogamicin (trade name: Mylotarg) for the treatment of CD33-positive acute myelogenous leukemia was approved by the USA Food and Drug Administration (FDA) in 2000." (PMID 34063812, 2021). "Since the approval of first ADC (Gemtuzumab ozogamicin (trade name: Mylotarg)) for the treatment of CD33-positive acute myelogenous leukemia, several ADCs have been developed for the treatment of cancer." (PMID 34063812, 2021). "Gemtuzumab ozogamicin is for the treatment of CD33-positive acute myeloid leukemia (AML) in first relapse in patients older than 60 years of age." (PMID 34063812, 2021). "The first ADC approved by the US Food and Drug Administration (FDA), in 2000, was Mylotarg (gemtuzumab ozogamicin), a mAb to CD33 conjugated to a calicheamicin derivative for the treatment of CD33+ acute myeloid leukemia." (PMID 33921632, 2021). "Since approximately 90–95% of patients with acute myeloid leukaemia express the CD33 protein on the surface of their leukaemic myeloblasts, it is an example of an ideal tumour-specific target for antibody therapy." (PMID 34063364, 2021). "CD33 single nucleotide polymorphisms (SNPs) have been implicated in the risk of Alzheimer's disease (AD) and the therapeutic efficacy of acute myeloid leukemia (AML)." (PMID 33796453, 2021). "In CD33-positive acute myeloid leukaemia (AML), leukemic blast cells are recognized by a specific anti-CD33 antibody that causes cytotoxicity due to its decoration with calicheamicins." (PMID 34299113, 2021). "An antibody which targets PD-1, CD3 and CD33 simultaneously has been developed and proved to be efficient in treating acute myeloid leukemia (AML) in preclinical experiments." (PMID 33941237, 2021). "A DNA-alkylating antitumor agent was conjugated to a humanized anti-CD33 antibody using sulfo-N-Succinimidyl 4-(2-pyridyldithio)-butanoate to form a CD33-targeting ADC for the treatment of acute myeloid leukemia (AML)." (PMID 34361141, 2021). "PBD has been used as a payload for the ADC, Vadastuximab talirine or SGN-CD33A being developed by Seattle Genetics to treat acute myeloid leukemia (AML) targeting CD33." (PMID 34440076, 2021). "Gemtuzumab (-ozogamicin) is an antibody against glycoprotein CD33, which is administered intravenously to treat acute myeloid leukemia (AML)." (PMID 32421085, 2020). "Monoclonal anti-CD33 conjugated to toxin-gemtuzumab ozogamicin (Mylotarg) was approved to treat patients with CD33-positive acute myeloid leukemia (AML)." (PMID 33297561, 2020). "CD33 is one of the earlier ADC markers targeted by gemtuzumab ozogamicin (MylotargTM) for the treatment of acute myeloid leukemia (AML)." (PMID 32111076, 2020). "AMV564 is a novel CD33/CD3 tetravalent bispecific antibody currently in early phase clinical trials for relapsed or refractory acute myeloid leukemia (AML) (NCT03144245)." (PMID 32296575, 2020). "The first disclosed phase I clinical trial was performed in three patients with acute myeloid leukemia (AML) with an infusion of NK-92 cells targeting CD33+ tumor cells." (PMID 32456165, 2020). "A bispecific CD33/CD3 BiTE antibody (AMG330) has been produced to manage the relapsed/refractory acute myeloid leukemia (AML) subjects (NCT02520427)." (PMID 33167514, 2020). "CD33 is a transmembrane receptor, and was found to express on myeloid and lymphoid cells in about 85%‐90% of patients with acute myeloid leukemia." (PMID 32207560, 2020).
acute myeloid leukemia (continued). "CD33 CAR-NK cells were produced in a GMP facility to be tested in a phase-I study for the treatment of patients with acute myeloid leukemia (AML)." (PMID 32707982, 2020). "The differentiation of HL-60 immature acute myeloid leukemia cells has been reported with decrease in the expression of early hematopoietic progenitor marker CD33 (Sialic Acid-Binding Ig-Like Lectin 3) and an increase of matured myeloid marker CD11b." (PMID 32698503, 2020). "A total of 12 Nbs were generated against recombinant CD33 protein, out of which six bound natively CD33 protein, expressed on the surface of acute myeloid leukemia THP-1 cells." (PMID 31906437, 2020). "CAR-NK-92 cell-based therapy is currently being evaluated in clinical trials for CD33+ acute myeloid leukemia (AML; NCT02944162) and CD7+ leukemia and lymphoma (NCT02742727)." (PMID 31156651, 2019). "Human CD33 on Acute Myeloid Leukaemia blasts has been successfully targeted by Gemtuzumab ozogamicin (GO), an anti-CD33 humanized antibody conjugated to calicheamicin in Phase III clinical trials." (PMID 31462392, 2019). "Our group extended this approach to RIT of acute myeloid leukemia (AML) using 111In-labelled anti-CD33 murine M195 and humanised HuM195 mAbs similarly modified with NLS peptides to promote nuclear importation." (PMID 31659527, 2019). "SGN-33A is currently enrolled in phase III clinical trials for the treatment of Acute Myeloid Leukemia (AML) where CD33 (sialic acid-binding sialo-adhesin receptor 3) is expressed on malignant cells in the vast majority of patients." (PMID 29409507, 2018). "Actimab-A, which represents 225Ac conjugated to lintuzumab (anti-CD33 mAb), demonstrated safety and efficacy against acute myeloid leukemia (AML) in two phase 1 trials." (PMID 29510568, 2018). "A CD33/CD3-bispecific BiTE construct called AMG330 has been designed to target acute myeloid leukemia (AML)." (PMID 28469973, 2017). "CLL1 and CD33 are cell surface antigens overexpressed in acute myeloid leukemia, and the antibody Fab fragments were coupled to either azido-PEG3-aminooxy or BCN-PEG3-aminooxy linkers, respectively." (PMID 29120405, 2017). "We developed an immunotherapeutic strategy targeting the CD33 myeloid antigen, expressed in ~ 85–90% of patients with acute myeloid leukemia, using chimeric antigen receptor redirected T-cells." (PMID 27907031, 2016). "213Bi-lintuzumab targeting CD33 has been successfully applied in clinical trials with patients suffering from acute myeloid leukemia." (PMID 25576914, 2015). "Two clinical studies are ongoing in the USA with an anti-CD33 antibody labeled with actinium-225 in patients with Acute Myeloid Leukemia." (PMID 25679452, 2015). "Recently, we showed the CD33 antibody Lintuzumab, which has been used safely in human acute myeloid leukemia trials, downregulates cell surface CD33 up to 80 % in PMA-differentiated U937 cells in vitro." (PMID 26438529, 2015). "The cancer-targeted therapy with targeting ligands includes leukocyte differentiation antigen (CD33) for acute myeloid leukemia, GD2 for neuroblastoma, and the folate receptor for wide human tumors." (PMID 24672796, 2014). "Gemtuzumab ozogamicin (GO), an immunoconjugate between an anti-CD33 antibody and a calicheamicin-γ1 derivative, induces remissions and improves survival in a subset of patients with acute myeloid leukemia (AML)." (PMID 23320091, 2013). "For example, Mylotarg® (gemtuzumab) is a currently FDA-approved monoclonal antibody against CD33 for the selective delivery of small molecule chemotherapeutics to acute myeloid leukemia (AML) cancer cells that overexpress CD33." (PMID 23667320, 2013). "In vivo ablation of CD33+ cells achieves good results when treating patients with acute myeloid leukemia." (PMID 22830977, 2012). "CD33 expression derived from flow cytometry predicted clinical outcome in patients with acute myeloid leukemia (AML) who were treated with gemtuzumab ozogamicin monotherapy." (PMID 22662133, 2012).
acute myeloid leukemia (continued). "With this strategy we redirected immune responses towards the CD33 antigen to target acute myeloid leukemia." (PMID 22272203, 2012). "Most recently, CIK cells were modified with a CD33-specific CAR for targeting acute myeloid leukemia cells and with a CD19-specific CAR with 4-1BB costimulatory signal for targeting B-lineage acute lymphoblastic leukemia." (PMID 22481963, 2012). "Gemtuzumab ozogamicin (GO) is a chemotherapy-conjugated anti-CD33 monoclonal antibody effective in some patients with acute myeloid leukemia (AML)." (PMID 21915304, 2011). "However, optimized dosing regimens allowed the reintroduction of two withdrawn drugs, including the ADC emtuzumab ozogamicin for CD33-positive acute myeloid leukemia." (PMID 41499516, 2026). "Gemtuzumab ozogamicin (GO) is indicated for CD33-positive acute myeloid leukemia (AML)." (PMID 38384285, 2024). "Among the currently FDA-approved antibody drug conjugates (ADCs), Mylotarg and Besponsa, which comprise the pH-sensitive hydrazone linkers derived from amino groups in drugs, target relapsed CD33 + acute myeloid leukemia (AML) and CD22 + B-cell acute lymphoblastic leukemia (B-ALL), respectively." (PMID 39054545, 2024). "Furthermore, another previous study has published the results of a phase I first-in-human clinical trial using CD33-CAR NK cells for relapsed or resistant acute myeloid leukemia patients." (PMID 39619199, 2024). "Consequently, in the year 2000, a substantial success was achieved in the development of ADC with the advent of the anti-CD33-targeted agent gemtuzumab ozogamicin for adults with acute myeloid leukemia." (PMID 37568702, 2023). "On 17 May 2000, GO received accelerated approval for the treatment of older patients with relapsed CD33-positive acute myeloid leukemia (AML), but the approval later was withdrawn based on safety and efficacy data in 2010." (PMID 37568702, 2023). "The field of ADCs has grown rapidly since the first ADC, gemtuzumab ozogamicin (Mylotarg®,), a humanised IgG4 antibody targeting CD33 and conjugated to the DNA-cleaving agent calicheamicin, was approved by the FDA in 2000 for the treatment of CD33-expressing acute myeloid leukaemia (AML)." (PMID 36980732, 2023). "Positive clinical outcomes were reported in phase I trials of 225Ac-lintuzumab, and a phase II study of 225Ac-lintuzumab monotherapy for older patients with untreated acute myeloid leukaemia is now in progress and is also being studied in a subset of patients with CD33-positive multiple myeloma." (PMID 37376167, 2023). "Current CAR-T therapies for acute myeloid leukaemia mostly target myeloid-lineage antigens, such as CD123 and CD33, which may be associated with potential haematopoietic toxicity." (PMID 36517851, 2022). "Notably, two CD33 antibodies, gemtuzumab ozogamicin (Mylotarg) and lintuzumab, have been tested in humans for treating acute myeloid leukemia and can effectively reduce cell surface CD33 expression in monocytes." (PMID 36012569, 2022). "CD33 mediates the proliferation and differentiation of myeloid cells and it can be detected on the malignant myeloid blasts in the majority of patients with acute myeloid leukemia (AML), suggesting it is a potential target for cancer immunotherapy." (PMID 34039409, 2021). "CD33 is a myeloid cell surface antigen that is expressed on blast cells in acute myeloid leukemia." (PMID 34638510, 2021). "Recently, this technology has also been applied to manipulate DCs, and it has been shown that DCs transduced with a CAR directed against CD33 (highly expressed on acute myeloid leukemia (AML) cells) are able to enhance anti-AML CAR T cell cytotoxicity in vitro." (PMID 34445143, 2021). "Roughly 85–90% of adult and pediatric acute myeloid leukemia (AML) are CD33-positive." (PMID 34203180, 2021). "Moreover, NK-92-derived CD33-CAR-NK cells were well-tolerated in a phase I trial of 3 patients with acute myeloid leukemia (AML) (NCT02944162)." (PMID 33499101, 2021).
acute myeloid leukemia (continued). "Gemtuzumab ozogamicin, a conjugate of humanized anti-CD33 monoclonal antibody covalently attached to the cytotoxic antitumor antibiotic calicheamicin, was firstly approved in 2000 under accelerated approval for treating CD33-positive acute myeloid leukemia (AML)." (PMID 33389713, 2021). "It was an anti-CD33 humanized antibody indicated for relapsed acute myeloid leukemia in 2000." (PMID 34440076, 2021). "Interestingly, already, in 2000, an anti-CD33 (= Siglec-3) antibody as part of an antibody–drug conjugate was approved for treating acute myeloid leukemia." (PMID 33670444, 2021). "Additionally, Nusrat Khan and his co-workers developed a CD33 targeting vector to express an inducible caspase-9 suicide gene in acute myeloid leukaemia therapy." (PMID 32272948, 2020). "Another Siglec that is being actively targeted in acute myeloid leukemia (AML) cells is CD33." (PMID 33333862, 2020). "Targeting CD33, the molecule expressed on healthy and neoplastic myeloid cells, to fight the acute myeloid leukaemia (AML) may result in off-tumour toxicity and destruction of healthy myeloid cells." (PMID 32722109, 2020). "In fact, the very first ADC to gain marketing approval by the US Food and Drug Administration (FDA) was gemtuzumab ozogamicin, consisting of a humanized anti-CD33 monoclonal antibody conjugated to the DNA-damaging agent calicheamicin, for the treatment of acute myeloid leukemia (AML)." (PMID 30783518, 2019). "Gemtuzumab ozogamicin (ɑ-CD33) is a recombinant humanized IgG4κ antibody, which is conjugated to a cytotoxic antitumor antibiotic directed against the CD33 antigen present on leukemic myeloblasts in acute myeloid leukemia." (PMID 31303962, 2019). "Therapeutic benefit of Ac-225 labeled anti-CD33 monoclonal antibody was evaluated in a phase-1 clinical trial in acute myeloid leukemia (AML) patients where median progression free survival (PFS) and median overall survival of 2.7 months and 5.5 months respectively were observed." (PMID 28562337, 2017). "A humanized antibody specific for a human myelogenous leukemia antigen (CD33) labeled with 213Bi was administered to 18 patients with Acute Myeloid Leukemia and results showed a reduction in circulating blasts in most patients (~80%), whereas no extramedullary toxicity was observed." (PMID 25679452, 2015). "The CD33 antigen is a transmembrane protein present on the surface of myeloid, megakaryocytic, erythroid and multipotent progenitor cells that is used as a cell surface marker for the clinical diagnosis and therapeutic targeting of acute myeloid leukemia." (PMID 23673681, 2013). "The results obtained using this system were similar to those obtained by means of flow cytometry, which suggests that the system could be used to detect CD33+ cells in marrow aspirates taken from patients with acute myeloid leukemia." (PMID 23673681, 2013). "Since the approval of the first ADC, gemtuzumab ozogamicin (Mylotarg®), targeting CD33 for acute myeloid leukemia (AML) in 2000, the global ADC landscape has expanded considerably." (PMID 41184856, 2025). "Designed for acute myeloid leukemia (AML), Mylotarg binds to CD33-expressing leukemic blasts, is internalized, and releases calicheamicin in the lysosomes, triggering double-stranded DNA breaks and apoptosis." (PMID 41041285, 2025). "The clinical landscape changed dramatically with the regulatory approval of gemtuzumab ozogamicin (GO) in 2000 for CD33-positive acute myeloid leukemia (AML)." (PMID 40805178, 2025). "Numerous studies have demonstrated that CD33 is a critical target antigen in acute myeloid leukemia (AML)." (PMID 40969269, 2025). "For example, the application of CD33-CAR-NK92 cells in patients with relapsed or refractory acute myeloid leukemia (AML) resulted in fever (reaching up to 40°C) and grade I CRS, accompanied by increased serum levels of IL-10 and IL-17." (PMID 40260240, 2025).
acute myeloid leukemia (continued). "Gemtuzumab ozogamicin (GO) is an antibody-drug conjugate that targets CD33, a marker expressed on most acute myeloid leukemia (AML) cells." (PMID 40691504, 2025). "The first ADC was granted FDA approval in 2000 for the treatment of acute myeloid leukemia (AML); gemtuzumab ozogamicin targets CD33 and carries N-acetyl-gamma-calicheamicin as the cytotoxic payload." (PMID 40501953, 2025). "Siglec-3 (CD33)-specific CAR-T cell therapy has shown efficacy in preclinical models of acute myeloid leukemia (AML) resistance and have begun clinical trial evaluation." (PMID 38725856, 2024). "Bone marrow evaluation confirmed the diagnosis of acute myeloid leukemia (AML), with myeloid blasts positive for CD33, CD34, CD13, and MPO on flow cytometry, and a significant monocytic component (M4 according to French-American-British (FAB) classification)." (PMID 39830569, 2024). "Naturally, about 90% of acute myeloid leukemia (AML) cases are CD33+, as defined by the abundant expression of the myeloid-specific antigen on more than 20–25% of immature leukemic blasts." (PMID 39770542, 2024). "Cells targeting the CD33 marker have also been successful, as it is expressed in myeloid cells and in 80-90% of patients with acute myeloid leukemia (AML)." (PMID 39091493, 2024). "In the first-in-human clinical trial, irradiated CAR-NK-92 cells were detectable 3 days after their infusion in two acute myeloid leukemia (AML) patients (NCT02944162, phase I trial of CD33-CAR NK-92 cells in three patients with RR-AML)." (PMID 39061247, 2024). "In myelodysplastic syndromes (MDS), neoplastic myeloblast (CD34+CD13+CD33+ cells) numbers often increase over time, leading to secondary acute myeloid leukemia (AML)." (PMID 37729123, 2023). "Based on the EFS benefit, the FDA later extended the indication of GO for newly diagnosed CD33-positive acute myeloid leukemia (AML) to include pediatric patients 1 month and older, on 16 June 2020." (PMID 37568702, 2023). "Since CD33 is widely distributed in normal and malignant cells in acute myeloid leukemia (AML), targeting it leads to serious myeloablation in treated patients." (PMID 37964355, 2023). "Typical tumor antigens include CD19 and HLA class II in B cell malignancies, CD30 in Hodgkin lymphoma, epidermal growth factor receptor (EGFR) in various epithelial cancers, HER2 in breast cancer, and CD33 in acute myeloid leukemia (AML)." (PMID 37457707, 2023). "The conjugated anti-CD33 monoclonal antibody, gemtuzumab ozogamicin (GO), is highly active against acute myeloid leukemia (AML), but dosing and scheduling issues have bedeviled its stable integration into routine clinical care regimens." (PMID 37595359, 2023). "In the first phase 1 dose-escalation study, 40 patients with relapsed or refractory CD33-positive acute myeloid leukemia (AML) were treated with 0.25 mg/m2 to 9 mg/m2 of gemtuzumab ozogamicin." (PMID 36765668, 2023). "Several randomized controlled trials have tested the addition of the CD33 antibody-drug conjugate gemtuzumab ozogamicin (GO) to intensive chemotherapy for adults with newly diagnosed acute myeloid leukemia (AML)." (PMID 35740603, 2022). "CD33 is a myeloid differentiation cell surface-expressed antigen present on acute myeloid leukemia (AML) blasts of a high percentage of patients." (PMID 35468841, 2022). "Initial Pre-clinical studies focusing on hematological cancers, targeting CD22 or CD33 in lymphoma and acute myeloid leukemia (AML), respectively, demonstrated promising anti-tumor activity." (PMID 36726355, 2022). "It has been used successfully in the treatment of acute myeloid leukemia (AML) based on its ability to bind to and destroy CD33-positive AML blast cells." (PMID 35892705, 2022). "Nevertheless, in acute myeloid leukemia (AML) the anti CD33 antibody-drug conjugate gemtuzumab ozogamicin is the only approved drug." (PMID 35740657, 2022). "The target-specific drug aptamer could inhibit CD33-positive acute myeloid leukemia." (PMID 35056696, 2022).